CAT (catalase)
Diseases named in the same sentence as CAT in open-access papers (continued):
Sharing a sentence is not in itself a finding about the gene and the disease.
tumor (continued). "The catalase can effectively improve the tumor hypoxic microenvironment, thus enhancing the sonodynamic treatment effect on large tumor models." (PMID 39992547, 2025). "For PDT to show better efficacy, researchers combined Pt nanoparticles with nanoparticle-based catalase-targeted delivery (CAT) to alleviate tumor hypoxia and improve PDT." (PMID 40486836, 2025). "The simultaneous overexpression of Parkin and Catalase significantly restored the lung metastatic capacity of tumor cells in mice overexpressing Parkin." (PMID 38424181, 2024). "The immobilized CAT facilitated the conversion of the tumor’s endogenous H2O2 into O2, persistently alleviating hypoxia within the TMEs." (PMID 38945949, 2024). "The MOF-888 enabled pH-responsive CAT detachment inside the cell and efficiently initiated ROS generation for photodynamic therapy of tumor cells." (PMID 38334515, 2024). "We then evaluated the effect of Catalase on the migratory ability of tumor cells by Transwell and wound healing assays." (PMID 38424181, 2024). "Actually, Ferrihydrites, functioning as inorganic CAT, have demonstrated in vivo their ability to produce O2 within the tumor microenvironment, leading to a substantial enhancement of the therapeutic effect of radiotherapy." (PMID 38638571, 2024). "This peroxynitrite subsequently reacts with leftover H2O2 to produce singlet oxygen, which deactivates catalase molecules on the surface of tumor cells." (PMID 39765910, 2024). "As the retained CAT triggers the biological decomposition of tumor endogenous H2O2 to produce O2, persistent hypoxia would be relieved, improving PDT efficacy and reversing immunosuppressive TME." (PMID 38544975, 2024). "Circulating antioxidants can also be involved in RONS utilization as evidenced by lowered SOD, CAT, vitamin C and vitamin E levels in the blood of OC patients to suggest a whole-body response to a growing tumor." (PMID 38397798, 2024). "Natural CAT and CAT-mimic nanozymes can be used in biomedical applications for preventing ROS-mediated cell membrane damage, treating inflammatory disorders, tumor cell growth inhibition, and environmental remediation (biodegradation of organic contaminants)." (PMID 38334515, 2024). "The addition of SOD and catalase to the assay restored NK cell degranulation, indicating that ROS-mediated NK cell death was responsible for their decreased anti-tumor activity." (PMID 39759523, 2024). "Despite their promising application potential in ROS-based therapeutic applications, natural CAT suffers due to poor thermal stability and easy inactivation under harsh acidic tumor environments." (PMID 38334515, 2024). "Next, we determined the effect on tumor cell migratory ability using Transwell and wound healing assays and found that overexpression of Catalase rescued the Parkin-mediated inhibition of cell migration in T24, 5637, and UM-UC-3 cells." (PMID 38424181, 2024). "The hybrid nanogels with an optimized ratio of LOx to CAT fatally damaged tumor cells by significantly increasing ROS levels in the cells, thus markedly inhibiting tumor growth." (PMID 37717209, 2024). "All genes, except PGLYRP2, were upregulated in tumor tissues, with significant increases found for CAT (P < 0.01), CXCL1 (P < 0.05), and RAF1 (P < 0.05), which agreed with the previous results." (PMID 38806963, 2024). "TRAIL overexpression increased MDA, while reduced the levels of SOD and CAT in tumor xenograft model compared with the pcDNA3.1-NC group (P < 0.01)." (PMID 38383815, 2024). "This process disables catalase on the surface of tumor cells, allowing H2O2 and peroxynitrite to accumulate and cause death via lipid peroxidation and the mitochondrial route." (PMID 39765910, 2024). "CAT released by tumour cells after the endocytosis of CSI@Ex-A catalyses the decomposition of hydrogen peroxide, thereby generating oxygen to mitigate tumour hypoxia." (PMID 38561367, 2024).
tumor (continued). "The differences in the functionality of direct antioxidant enzymes are typically evident as reduced catalase and superoxide dismutase activities in tumor tissues compared to the corresponding adjacent tumor-free tissue." (PMID 39334568, 2024). "CLSM observation of the tumor tissues confirmed these results, with the highest fluorescent signal of CD8+ CTLs observed in tumor sections from mice treated with NanoICD/CAT-PCA." (PMID 38324678, 2024). "Concurrently, the 17-DMAG-loaded DE532 Ex demonstrated the lowest suppression of antioxidant enzymes, such as superoxide dismutase 2 and catalase, within tumor tissues." (PMID 39201449, 2024). "Simultaneously, H2S further increases intracellular H2O2 levels by inhibiting CAT activity, providing a continuous substrate for the Fenton reaction, thereby enabling cascade ferroptosis in tumor cells." (PMID 39665080, 2024). "For instance, a dual nanozyme Au2Pt-PEG-Ce6 has been shown to have catalase activity, which generates O2 in cancer cells and has enhanced anti-tumor activity in cervical cancer models when combined with PDT therapy." (PMID 37273798, 2023). "CAT has been found to promote energy expenditure and metabolism, inhibit fat accumulation, antioxidant, anti‐inflammatory, and anti‐tumor properties." (PMID 36890785, 2023). "Our data also confirm that CAT is expressed at higher levels in both stool and tumor tissue of CRC patients than in normal samples." (PMID 37313408, 2023). "It has been proposed that hypoxia can be relieved by hyperbaric oxygen inhalation, manganese dioxide or catalase as catalysts, or in situ oxygen production in the tumor microenvironment." (PMID 37120558, 2023). "4T1 and CT26 cell lines were chosen because previous studies have shown that catalase can contribute to slower tumor growth in combination with radiation and/or chemotherapy in these tumor models." (PMID 37311396, 2023). "Next, we inoculated mice with the tumor cell lines expressing intracellular catalase (4T1-or CT26-CAT) or the control (4T1-or CT26-control)." (PMID 37311396, 2023). "Mice bearing established 4T1 or CT26 tumors were treated with CAT-ABP + alum as before and given a single dose of x-ray RT (6–9 Gy) localized to the tumor on day 5 following the first dose of catalase." (PMID 37311396, 2023). "CAT catalyzes the conversion of hydrogen peroxide (H2O2) in the tumor microenvironment (TME) into oxygen (O2), providing sufficient substrate for HPPH-mediated PDT, boosting intratumoral reactive oxygen species (ROS) levels under light conditions." (PMID 38139233, 2023). "In the presence of tumor endogenous hydrogen peroxide, it has been proposed that catalase can generate oxygen, potentially decreasing hypoxia." (PMID 37311396, 2023). "Despite a few significantly differentially expressed genes, we do not observe a larger signature across these gene sets that would suggest catalase is significantly modifying the level of hydrogen peroxide or oxygen in these tumor models." (PMID 37311396, 2023). "The two cancer-related genes displaying the strongest signals of positive selection, cadherin-1 (CDH1) and catalase (CAT), also play roles in tumor development." (PMID 37728212, 2023). "The reason is that hydrogen peroxide acts as a reactive substrate for molecules such as catalase, alleviating hypoxia in the tumor microenvironment." (PMID 37575228, 2023). "Through two independent validation cohorts, we finally identified five fecal tumor immune-related proteins (CAT, LTF, MMP9, RBP4, and SERPINA3) as well as a biomarker panel that had definite diagnostic value for CRC." (PMID 37313408, 2023). "Previous studies have suggested that exogenous catalase can contribute to efficacy in mouse tumor models." (PMID 37311396, 2023). "Among these genes, we identified several factors that were related to tumor progression and were found to be consistent with previously reported, for example, CAT, ATP1B1, CCND1, and CXCL12." (PMID 38020927, 2023).
tumor (continued). "Previous studies have shown that catalase can contribute to efficacy in certain mouse tumor models, but the results, context, and mechanistic explanations are inconsistent across studies." (PMID 37311396, 2023). "The in situ oxygen generation method uses catalase or metal-based catalysts to accelerate the decomposition of tumor-overproduced hydrogen peroxide (H2O2) into oxygen." (PMID 36900370, 2023). "This involves encapsulating catalase (CAT) into silica nanoparticles (CAT@SiO2) to alleviate tumor hypoxia, and then loading it with the sonosensitizer indocyanine green, which significantly improves the efficacy of SDT." (PMID 37456742, 2023). "One difference of our approach for tumor-localized extracellular catalase is the use of alum-anchoring." (PMID 37311396, 2023). "The catalase decomposes the tumor-overproduced H2O2 into oxygen, and the oxygen is then reserved in the perfluoropolyether for PDT." (PMID 36900370, 2023). "Song designed a novel bionanoreactor to decompose tumor endogenous H2O2 and relieve tumor hypoxia by encapsulating CAT in tantalum oxide (TaOx) nanoshells, resulting in TaOx@Cat nanoparticles." (PMID 36703877, 2023). "In metastatic models, catalase has been demonstrated to reduce the number of disseminated tumor cells and prolong survival, an action attributed to depletion of hydrogen peroxide." (PMID 37311396, 2023). "Subsequently, they delivered a NIR light-responsive hydrogel system (HMI@GEL) after loading metformin (Met) to block the energy supply of the tumor and catalase-mimicking Hemin@mil88 to effectively alleviate tumor hypoxia." (PMID 37102898, 2023). "CuNPs and/or low-dose gamma radiation treatment increased oxidative stress state as presented by the elevation in MDA levels and decreased antioxidant state as presented by the depression of GSH content and CAT activity compared to the untreated tumor group." (PMID 36905557, 2023). "We also engineered the 4T1 and CT26 tumor cell lines to over-express catalase in a doxycycline (DOX)-inducible manner, by lentiviral transduction." (PMID 37311396, 2023). "Alexa Fluor 647 (AF647)-labeled CAT-ABP was injected subcutaneously (s.c) in non-tumor bearing mice or i.t. into apigmented B16F10 tumors and the retention at the injection site was tracked for 7 days." (PMID 37311396, 2023). "They found that antioxidant enzymes including SOD2 and CAT were decreased, while DNA repair enzymes were imbalanced (i.e., were both over- and under-expressed when compared to non-tumor tissue), and this abnormality generated MSI." (PMID 37835526, 2023). "Several efforts have been conducted to overcome tumor hypoxia, such as water splitting, respiratory inhibitor, O2-evolving agents, catalase, and nanoscale metal-organic framework." (PMID 37007107, 2023). "The therapeutic action of catalase has been attributed to direct consequences of its enzymatic activity, either through increasing oxygen or decreasing hydrogen peroxide in the tumor microenvironment." (PMID 37311396, 2023). "We studied the efficacy of catalase cancer therapy in subcutaneous syngeneic mouse tumor models with a further aim to elucidate potential mechanisms of action." (PMID 37311396, 2023). "In conclusion, we successfully developed a novel class of M1 macrophage membrane-camouflaged nanoparticles based on CAT to relieve tumor hypoxia, which exhibited significant metastasis inhibition and an excellent antitumor effect." (PMID 37765212, 2023). "We suggest that metrics other than NQO1:CAT should be considered when characterizing a HNSCC tumor and its capacity to respond to β-lapachone." (PMID 36978989, 2023). "In this work, we evaluate the efficacy of tumor-localized extracellular and intracellular catalase in subcutaneous syngeneic mouse tumor models." (PMID 37311396, 2023).
tumor (continued). "To do this, we engineered two approaches to maximize intratumoral catalase exposure: 1) an injected extracellular catalase with enhanced tumor retention, and 2) tumor cell lines that over-express intracellular catalase." (PMID 37311396, 2023). "The octahedral nanoceria with Ce3+/Ce4+ of 0.1/0.9 demonstrated a more effective catalase-mimicking activity relieving tumour hypoxia." (PMID 36656411, 2023). "A key component to many of these studies is attempting to maximize and maintain catalase exposure at the tumor site." (PMID 37311396, 2023). "CAT-Ce6, as an amphiphilic complex, can avoid the aggregation of Ce6 in the aqueous solution, improving biocompatibility and distribution of Ce6 in tumor tissues." (PMID 37915541, 2023). "Experimental models have demonstrated that low concentrations of extracellular singlet oxygen, generated by illuminating the photosensitizer photofrin, locally deactivate catalase on tumor cell membranes." (PMID 38069213, 2023). "Recent studies have shown that water-soluble catalase or MnO2 NPs carried by specific nanomaterials can directly generate oxygen in tumour tissue to alleviate tumour hypoxia." (PMID 37993847, 2023). "Subsequently, the in vivo tumor suppression efficacy of LOX and CAT dual enzyme-displaying AaLS was evaluated using CT26 tumor-bearing mice." (PMID 36597089, 2023). "We confirmed that the retained protein is functional by measuring catalase activity of homogenized tumor samples 4 days after i.t. injection." (PMID 37311396, 2023). "The tumor volume in the CAt‐treated group on day 25 was 449.54 ± 217.26 mm3, whereas that in the vehicle group was 1,780.64 ± 57.45 mm3." (PMID 35592288, 2022). "As a natural antioxidant enzyme, CAT suffers from limited retention in tumour sites, leading to the limited generation of O2 in deep hypoxic areas." (PMID 36277398, 2022). "CAT at BSNSs-CAT efficiently catalyzed the conversion of H2O2 into O2 after BSNSs-CAT accumulated in tumor tissues through enhanced penetration and retention effect (EPR effect)." (PMID 35250594, 2022). "The percentage of O2 saturation concentration treated with BSNSs-CAT increased significantly from 52.5% to about 59.2% in the tumor site." (PMID 35250594, 2022). "Catalase (CAT) can catalyze the decomposition of endogenous H2O2 overexpressed in tumor tissues to generate oxygen." (PMID 36195918, 2022). "With hemin incorporation, the DF transformed into DNA nanozyme with catalase-mimic activity for in-situ oxygenation to relief tumor hypoxia." (PMID 36109814, 2022). "The experiment of combined radiotherapy and chemotherapy showed that the combination of CAT@Pt (IV) and liposome had the best inhibitory effect on tumor growth." (PMID 36147526, 2022). "Antioxidative enzymes such as catalase, superoxide dismutase, and glutathione peroxidase are expressed at a lower extent in tumor cells in comparison to normal cells, thus increasing tumor vulnerability to ROS." (PMID 35467257, 2022). "In detail, this light-triggered in situ gel released CAT to break down endogenous H2O2 in tumor cells under light irradiation, thus resulting in increased O2 concentrations in TME." (PMID 35910806, 2022). "The resistance of tumor cells to intercellular ROS signals depends on the expression of catalase on the cell membrane." (PMID 36326969, 2022). "An in vivo study was developed to observe the accumulation of catalase@MON NPs in the tumor by enhanced permeability and retention effect (EPR), which mediates the breakdown of endogenous H2O2 into oxygen." (PMID 36505711, 2022). "Applying a cream containing HB to the tumor site or injecting it inside the tumor would significantly reduce catalase activity and increase the number of hydrogen peroxide, and in that way, the tumor cells would take themselves into apoptosis." (PMID 36326969, 2022). "In the tumor microenvironment, the MoO3−x NUs behaved like CAT to catalyze the decomposition of H2O2, supplying abundant O2 for the following reaction." (PMID 35384520, 2022).
tumor (continued). "Only tumor cells (resistant to apoptotic stimuli) have persistently shown low levels of CAT protein and activity and high levels of ROS." (PMID 36555526, 2022). "The assembled DNA nanoparticles can effectively load photosensitizers and CAT, and accurately target tumor cells." (PMID 36147526, 2022). "Obviously, the combination of proteins and small-molecule drugs, such as therapeutic proteins/chemotherapeutics, therapeutic proteins/photosensitizers, and CAT/photosensitizers, results in enhanced synergistic anti-tumor effects in preclinical trials." (PMID 36147526, 2022). "The levels of OS markers (catalase, glutathione peroxidase, and glutathione system in serum; 8-oxo-7′8-dihydro-2′-deoxyguanosine and F2-isoprotanes in urine) and tumor and metabolic factors were determined." (PMID 35326149, 2022). "After entering into tumor cells, this nanoplatform underwent acidic degradation to form Zn ions, CAT Dz, free FeCysPW core and imidazole ligands." (PMID 35119544, 2022). "LLC tumor‐bearing mice were intravenously injected with Cy5.5‐labelled free CAT, DDRi@CAT‐M1Exos and DDRi@CAT‐PD‐M1Exos." (PMID 35715382, 2022). "Recently, researchers developed various biomaterials and therapeutic agents to alleviate tumor hypoxia, including hemoglobin, catalase (CAT), manganese dioxide NPs, oxygen-shuttle nanoperfluorocarbon (nanoPFC), hyaluronidase (HAase), and metformin (Met) 41-46." (PMID 34987658, 2022). "The catalase-mimetic activity of RuO2 was activated after being exposed to the tumor microenvironment, and immediately convert H2O2 to oxygenate the IR-808-Br2 for the photodynamic process under near-infrared irradiation." (PMID 35193573, 2022). "The in vivo fluorescence imaging was monitored, the ex vivo fluorescence imaging of tumors and major organs was performed, the biodistribution of Cy5.5 in tumors and organs was quantified, and the concentration of CAT and DDRi in tumor was precisely measured." (PMID 35715382, 2022). "Intravenously injected free CAT had negligible effect on reliving tumor hypoxia, which resulted from the short blood circulation time, lack of tumor‐targeting ability, and ease of digestion by enzymes in the blood." (PMID 35715382, 2022). "Among these nanoenzymes, cerium oxide (CeO2) nanomaterials can be applied as candidates for the development of tumor therapeutic nanoplatforms due to their catalase and peroxidase activity toward high H2O2 in tumor microenvironment at various pH values." (PMID 36015343, 2022). "As a result, CAT@Pt(IV)-liposome-mediated chemotherapy and enhanced RT effectively inhibited the growth of subcutaneous 4T1 tumor in living mice." (PMID 35119544, 2022). "The metal-based materials and catalase have their distinct strengths and limitations for tumor H2O2 decomposition." (PMID 35053229, 2022). "Except for the applications of MnO2, CeO2 and TiO2, CAT is also commonly used as a catalyst to ameliorate tumor hypoxia in PDIT." (PMID 35910806, 2022). "It was shown that PEG-catalase inhibited cell survival, adhesion, invasion, and proliferation due to the induction of tumor dormancy." (PMID 35326089, 2022). "CAT can protect cells from tumor initiation and progression, due to its role in preventing the accumulation of dangerous levels of oxidants." (PMID 36112236, 2022). "In order to examine the CAT function of relieve tumor hypoxia, tumors were collected 6 h after the last irradiation for examining the expression level of HIF‐1α by western blotting." (PMID 35715382, 2022). "The treatment of cancer cells with (+)-catechin resulted in a significant decrease in catalase level and an upgrade of the ROS level, which hence led to the inhibition of tumor cell growth and ultimately pushed the tumor toward apoptosis." (PMID 36193154, 2022).